COMMD1 (copper metabolism domain containing 1)
Description:
Scaffold protein in the commander complex that is essential for endosomal recycling of transmembrane cargos; the commander complex is composed of the CCC subcomplex and the retriever subcomplex. Can modulate activity of cullin-RING E3 ubiquitin ligase (CRL) complexes by displacing CAND1; in vitro promotes CRL E3 activity and dissociates CAND1 from CUL1 and CUL2. Promotes ubiquitination of NF-kappa-B subunit RELA and its subsequent proteasomal degradation. Down-regulates NF-kappa-B activity. Involved in the regulation of membrane expression and ubiquitination of SLC12A2. Modulates Na(+) transport in epithelial cells by regulation of apical cell surface expression of amiloride-sensitive sodium channel (ENaC) subunits and by promoting their ubiquitination presumably involving NEDD4L. Promotes the localization of SCNN1D to recycling endosomes. Promotes CFTR cell surface expression through regulation of its ubiquitination. Down-regulates SOD1 activity by interfering with its homodimerization. Plays a role in copper ion homeostasis. Involved in copper-dependent ATP7A trafficking between the trans-Golgi network and vesicles in the cell periphery; the function is proposed to depend on its association within the CCC complex and cooperation with the WASH complex on early endosomes. Can bind one copper ion per monomer. May function to facilitate biliary copper excretion within hepatocytes. Binds to phosphatidylinositol 4,5-bisphosphate (PtdIns(4,5)P2). Involved in the regulation of HIF1A-mediated transcription; competes with ARNT/Hif-1-beta for binding to HIF1A resulting in decreased DNA binding and impaired transcriptional activation by HIF-1. Negatively regulates neuroblastoma G1/S phase cell cycle progression and cell proliferation by stimulating ubiquitination of NF-kappa-B subunit RELA and NF-kappa-B degradation in a FAM107A- and actin-dependent manner.
Synonyms: C2orf5; MURR1; MGC27155
Tractability: Antibody: UniProt places it where antibodies can reach, with high confidence. PROTAC: UniProt records ubiquitination sites on it; ubiquitination databases record sites on it; its protein half-life has been measured.
Gene: Protein-coding gene on chromosome 2 (61,888,724 to 62,147,629, forward strand). Ensembl gene ENSG00000173163.
Subcellular location: Nucleus; Cytoplasm; Endosome membrane; Cytoplasmic vesicle; Early endosome; Recycling endosome
Subcellular location (Human Protein Atlas): Nucleoplasm; Cytosol
Pathways (Reactome):
Metabolism of proteins: Neddylation
Gene Ontology:
Molecular function: copper ion binding; identical protein binding; phosphatidic acid binding; phosphatidylinositol-3,4,5-trisphosphate binding; phosphatidylinositol-3,4-bisphosphate binding; phosphatidylinositol-3,5-bisphosphate binding; phosphatidylinositol-4,5-bisphosphate binding; protein binding; protein homodimerization activity; sodium channel inhibitor activity
Biological process: copper ion homeostasis; Golgi to plasma membrane transport; negative regulation of protein localization to cell surface; negative regulation of sodium ion transmembrane transport; negative regulation of transcription by RNA polymerase II; nucleotide-excision repair; plasma membrane to endosome transport; positive regulation of protein ubiquitination; regulation of proteasomal ubiquitin-dependent protein catabolic process; endocytic recycling
Cellular component: Cul2-RING ubiquitin ligase complex; cytoplasm; cytoplasmic vesicle; cytosol; early endosome; endosome membrane; nucleoplasm; nucleus; protein-containing complex; recycling endosome; endoplasmic reticulum membrane; endosome
Genetic constraint (gnomAD): Loss-of-function variants: 9 observed, 14.07 expected, observed/expected ratio (o/e) 0.64, 90% interval 0.38 to 1.12. The upper end of that interval is the gene's LOEUF score, 1.12, which puts it in group 4 of 6, group 1 being the genes least tolerant of losing a copy. Missense variants: 227 observed, 203.55 expected, observed/expected ratio (o/e) 1.12, 90% interval 1 to 1.25. Synonymous variants: 81 observed, 80.01 expected, observed/expected ratio (o/e) 1.01, 90% interval 0.85 to 1.22.
Homologues: Orthologues: chimpanzee COMMD1 (99% identical), macaque COMMD1 (99% identical), pig COMMD1 (90% identical), rabbit COMMD1 (89% identical), guinea pig COMMD1 (87% identical), mouse Commd1 (84% identical), dog COMMD1 (74% identical), rat Commd1 (73% identical), tropical clawed frog commd1 (58% identical), zebrafish commd1 (51% identical).
Diseases named in the same sentence as COMMD1 in open-access papers:
COMMD1 is named in the same sentence as 57 diseases in open-access papers, as found by Europe PMC text mining. Sharing a sentence is not in itself a finding about the gene and the disease. The quoted sentences say what the papers report.
Wilson disease (14 papers, 2010 to 2025). A very rare inherited multisystemic disease presenting non-specific neurological, hepatic, psychiatric or osseo-muscular manifestations due to excessive copper deposition in the body. "COMMD1-deficient dogs develop hepatic copper storage disease and chronic hepatitis similar to human Wilson’s disease." (PMID 32053895, 2020). "In this study, we demonstrated use of autologous gene-corrected liver organoids for cell transplantation in a canine COMMD1-deficient model of copper storage disease, which closely resembles human Wilson’s disease." (PMID 32053895, 2020). "COMMD1-deficiency in dogs leads to hepatic copper accumulation and chronic hepatitis representing a Wilson’s disease like phenotype." (PMID 22879914, 2012). "Indeed, Bedlington terriers with a null mutation in COMMD1 accumulate very high levels of copper, which can exceed 10,000 mg Cu/g dry liver weight, similar to what is seen in humans with Wilson's disease." (PMID 33262129, 2021). "To identify whether any biochemical change in WD correlates with any change in COMMD1 or whether COMMD1 is mutated in atypical Wilson disease patients, we screened the three exons and a large part of the exon-intron boundaries of COMMD1 in 109 patients." (PMID 20550661, 2010). "The similarity of symptoms between canine copper toxicosis and Wilson’s disease (WD) with atypical phenotypes has led to the idea of a possible role of COMMD1 in patients with WD." (PMID 39453175, 2024). "There is no indication that COMMD1 gene mutation induces human copper metabolic-related disorders such as Wilson’s disease, while numerous pieces of evidence indicate that COMMD1 is involved in the regulation of copper metabolism." (PMID 36776284, 2023). "As concerns COMMD1, its overexpression in HEK 293 cells was shown to enhance degradation of stably expressed ATP7B in wild type as well as Wilson disease-mutated cells." (PMID 32668621, 2020). "Studies on the Wilson disease protein showed that COMMD1 participates in the ATP7B-mediated copper-excretion pathway." (PMID 21483833, 2011). "It is primarily associated with a recessive mutation in the COMMD1 gene, also known as MURR1, an interacting ATP7B protein, which impairs hepatic copper excretion and leads to copper accumulation in the liver as observed in Wilson disease." (PMID 41480142, 2025). "The COMMD1-deficient dog model is thus not the exact copy of Wilson’s disease, but shows all relevant features of human chronic hepatitis." (PMID 22879914, 2012). "In dogs, mutations in the copper metabolism domain-containing 1 (COMMD1) gene lead to an autosomal recessive copper toxicosis associated with defective biliary excretion of copper resulting in massive hepatic copper accumulation and displaying many hallmarks of Wilson’s disease." (PMID 37920327, 2023). "Close resemblance of copper toxicosis symptoms to Wilson disease led to the idea of examining the role of COMMD1 in WD patients particularly with atypical phenotypes." (PMID 20550661, 2010). "This idea is based mainly on the findings from the most well-studied disease of Cu overload (Wilson disease), first identified in humans and involving the “Cu pump” ATP7B, and on findings for Cu overload in dogs involving other proteins required for putting Cu into bile, namely COMMD1 and ABCA12." (PMID 32668621, 2020).
lung carcinoma (10 papers, 2012 to 2024). "COMMD1 causes tumor apoptosis in lung cancer by suppressing SOD1 expression, and in neuroblastoma, elevated nuclear expression of COMMD1 inhibits cyclin D1 expression, G1/S transition, and tumor cell proliferation." (PMID 34493238, 2021). "Inhibition of COMMD1 expression stimulated the growth of tumor cells in lung cancer, neuroblastoma, head and neck squamous cell carcinoma, and prostate cancer." (PMID 36776284, 2023). "It is worth noting that COMMD1 promoted the repair of DNA double-strand breaks (DSBs) in lung cancer cells." (PMID 36776284, 2023). "Similar to the effect in lung cancer, COMMD1 exerts an anti-tumor effect in malignant tumors, including prostate cancer, diffuse large B-cell lymphoma, head and neck squamous-cell carcinoma (HNSCC), and neuroblastoma." (PMID 36776284, 2023). "In lung cancer, prostate cancer, and neuroblastoma, for example, COMMD1 exerts anti-tumor actions via inhibiting NF-κB." (PMID 36776284, 2023). "COMMD1 expression showed a positive correlation with the gene ontology (GO) DNA repair gene set enrichment signature in lung cancer samples." (PMID 33669398, 2021). "In the present study, we show the role of COMMD1 in CIGB-552 mechanism of action by generating the COMMD1 knock-out from the human lung cancer cell line NCI-H460." (PMID 33396282, 2020). "The interaction between COMMD1 and the synthetic peptides L-2, L-20, and CIGB-552 was evaluated by pull-down analysis in human lung cancer cells H460, following Western blot with specific COMMD1 antibody." (PMID 23401744, 2013). "It was found in this study that the treatment of lung cancer cells with CIGB-552 increased the levels of the protein COMMD1 in the cytoplasm and nucleus." (PMID 23401744, 2013). "Since our interest in this study is focused on the human lung cancer, the levels of the protein COMMD1 in the cytoplasm and nucleus of the H460 cells treated with CIGB-552 were evaluated by Western blot." (PMID 23401744, 2013). "Here, we found that the treatment of the lung cancer cells with CIGB-552 impaired the SOD1 activity and it could be associated with the accumulation of COMMD1." (PMID 23401744, 2013). "By activating COMMD1, CIGB-552 reduced the growth of breast cancer cells MCF-7 and colon cancer cells HT-29 in addition to lung cancer cells." (PMID 36776284, 2023). "The protein-protein interaction between COMMD1 and CIGB-552 and the accumulation of COMMD1 were also observed in lung cancer cells influenced by CIGB-552." (PMID 36776284, 2023). "COMMD2 is the second member of the copper metabolism MURR1 domain protein family, in which COMMD1 inhibits GBM cell proliferation and promotes lung cancer cell apoptosis." (PMID 34781885, 2021). "In addition to COMMD1, additional COMMD protein family members have showed promise as prospective lung cancer therapeutic targets." (PMID 36776284, 2023).
neuroblastoma (5 papers, 2014 to 2024). Neuroblastoma (NB) is the most common solid, extracranial childhood tumor. "Subsequently, DRR1 and COMMD1 inhibits cyclinD1 expression, the G1/S transition, and neuroblastoma cell proliferation." (PMID 36776284, 2023). "COMMD1 decreases tumor cell activity by inhibiting the NF-κB signaling pathway in prostate cancer and neuroblastoma." (PMID 36776284, 2023). "In neuroblastoma cells, COMMD1 can form a complex with other proteins to inhibit cyclin D1 expression, G1/S transition, and proliferation." (PMID 34493238, 2021). "Similar to the effect in HEK293T cells, COMMD1 also augmented mSOD1 aggregation in the neuroblastoma cell line Neuro2A, as demonstrated by mutants G85R and G93A." (PMID 24691167, 2014). "COMMD1 increases its stability by forming a complex with DRR1 and F-actin in the nucleus of neuroblastoma." (PMID 36776284, 2023). "DRR1, F-actin and COMMD1 form a complex in the nucleus, and the stability of COMMD1 in the complex is enhanced to promote the degradation of Nf-κB; DRR1 and COMMD1 inhibit cyclinD1 expression, G1/S transition and cell proliferation in neuroblastoma." (PMID 36776284, 2023).
ovarian carcinoma (5 papers, 2016 to 2023). A malignant neoplasm originating from the surface ovarian epithelium. "Ovarian cancer cells A2780 are more susceptible to cisplatin when nuclear COMMD1 expression is increased." (PMID 36776284, 2023). "Taken together, these results show that nuclear levels of COMMD1 are associated with cisplatin sensitivity in ovarian cancer cells." (PMID 27788210, 2016). "We here found that nuclear COMMD1 is associated with the response to cisplatin in ovarian cancer cells in vitro, and might be related to response to cisplatin treatment in ovarian cancer patients." (PMID 27788210, 2016). "We show that increased levels of nuclear COMMD1 affect cisplatin sensitivity in ovarian cancer cells in vitro, and that nuclear COMMD1 expression in ovarian cancer tumor tissue is associated with improved response to cisplatin treatment in one out of two analyzed patient cohorts." (PMID 27788210, 2016). "Furthermore, COMMD1 is associated to drug resistance in ovarian cancer and multiple myeloma." (PMID 36776284, 2023). "Another study showed that elevated nuclear expression of COMMD1 in ovarian cancer cells resulted in cisplatin sensitivity and led to the accumulation of cells in S phase." (PMID 33669398, 2021). "As another example, COMMD1 was under-expressed in ovarian cancer, and the lack of detectable COMMD1 protein expression was more frequent in ovarian cancer; COMMD1 was also shown to be related to the cisplatin sensitivity in ovarian cancer." (PMID 34627275, 2021). "HMGB1 and HMGB2 genes were silenced in SKOV-3 and PEO1 EOC cell lines and levels of mRNA from 4 detected interacting partners of HMGB1 or HMGB2 in ovary cancer, COMMD1, MIEN1, NOP53 and ZNF428, were analyzed by qRT-PCR as explained in Materials and Methods." (PMID 32867128, 2020). "Although to a lesser extend, similar results were seen in the ovarian cancer cell line Peo14 in which we stably increased COMMD1 expression." (PMID 27788210, 2016). "Expression of COMMD1 was observed in all ovarian cancer samples, however, specifically nuclear expression of COMMD1 was only observed in a subset of ovarian cancers." (PMID 27788210, 2016). "We evaluated the role of COMMD1 in cisplatin sensitivity in A2780 ovarian cancer cells and the relation between COMMD1 expression and response to platinum-based therapy in advanced stage high-grade serous ovarian cancer (HGSOC) patients." (PMID 27788210, 2016). "In this study, we investigated the role of COMMD1 in cisplatin sensitivity, and assessed COMMD1 expression in two cohorts of patients treated for advanced stage ovarian cancer." (PMID 27788210, 2016). "Taken together, our data suggest that elevated levels of nuclear COMMD1 confer A2780 ovarian cancer cells to be more sensitive to platinum-based chemotherapy." (PMID 27788210, 2016). "Taken together, these results suggest that nuclear expression of COMMD1 sensitize ovarian cancer to cisplatin, possibly by modulating the G2/M checkpoint and through controlling expression of genes involved in DNA repair and apoptosis." (PMID 27788210, 2016). "Next, we determined the COMMD1 levels in A2780/Cp70 cells, an ovarian cancer cell line, which is 13-fold more resistant to cisplatin than A2780 cells." (PMID 27788210, 2016). "We found that elevation of nuclear COMMD1 expression sensitized A2780 ovarian cancer cells to cisplatin-mediated cytotoxicity." (PMID 27788210, 2016). "Next, we stained COMMD1 in a panel of whole sections of ovarian cancer tissues (n = 21), and observed COMMD1 expression in all samples." (PMID 27788210, 2016). "To this end, we stably overexpressed FLAG-tagged COMMD1 in A2780 ovarian cancer cells." (PMID 27788210, 2016). "The relation between subcellular COMMD1 localization and response of ovarian cancer patients to therapy and survival was not established previously." (PMID 27788210, 2016).
breast carcinoma (4 papers, 2013 to 2023). "Since ATP1B1 transcript has been reported to be upregulated in response to copper overload, this provides an initial hint that, similar to Commd1, Commd3 deficiency causes changes in copper homeostasis in breast cancer." (PMID 37072858, 2023). "Additionally, nuclear COMMD1 was suggested to participate in the cellular response to DNA damage, through its ability to interact with the DNA repair proteins Breast Cancer 1 Early Onset (BRCA1), BRCA1-associated RING domain protein 1 (BARD1) and Checkpoint kinase 2 (Chk2)." (PMID 27788210, 2016). "In contrast, showed that depletion of COMMD1 resulted in hypersensitivity of breast cancer cells to the DNA damaging agents’ cisplatin and doxorubicin." (PMID 33669398, 2021). "We were able to replicate the enhanced cisplatin sensitivity in the breast cancer cell line MDA-MB-231 upon COMMD1 silencing, which would indicate that the effects of COMMD1 on cisplatin response and tumor behavior are cell-type specific." (PMID 27788210, 2016). "Remarkably, our results on the role of COMMD1 in cisplatin sensitivity are in contradiction with prior data that demonstrated that reduced levels of COMMD1 in a breast cancer cell line and a hepatoma cell line lead to increased cisplatin sensitivity." (PMID 27788210, 2016).
colorectal cancer (4 papers, 2018 to 2024). A primary or metastatic malignant neoplasm that affects the colon or rectum. "They identified recurrent DNA amplifications, and gain of chromosomic region mapping the locus of COMMD1, COMMD5, and COMMD3 have been reported in lymphoma, leukemia, colorectal cancer, hepatocellular carcinoma, and oral squamous cell carcinoma." (PMID 33768002, 2021).
hepatoma (4 papers, 2011 to 2025). "Conversely, our discovery of COMMD1 as a potential target gene for hepatocellular carcinoma treatment is crucial for personalized therapy in patient management." (PMID 40109870, 2025). "We propose that elevated COMMD1 expression decreases copper ion levels in hepatocellular carcinoma cells, thereby diminishing the cytotoxic effects of cuproptosis on these cells." (PMID 40109870, 2025). "Whereas we previously demonstrated that COMMD1 expression augments the protein degradation of ATP7B in vitro, others have shown a decline in Atp7b expression after depletion of Commd1 in the mouse hepatoma Hepa1-6 cells." (PMID 22216203, 2011).
prostate carcinoma (4 papers, 2016 to 2023). A carcinoma that arises from epithelial cells of the prostate gland. "sCLU promotes COMMD1 and I-κB degradation, enhances Nf-κb activity and tumor cell survival in prostate cancer cells." (PMID 36776284, 2023). "COMMD1 is an important negative regulator of NF-κB, while activation of canonical NF-κB signaling increases prostate cancer cell survival." (PMID 34493238, 2021). "In contrast, in many other types of cancer (e.g. seminoma, ovarian, breast, and prostate cancer) a reduced expression of COMMD1 has been found." (PMID 27788210, 2016).
colitis (3 papers, 2022 to 2025). Inflammation of the colon. "This highlights the anti-inflammatory role of COMMD1, with its deficiency potentially increasing the risk of colitis-associated cancer." (PMID 40370501, 2025). "COMMD1 also promotes inflammation and protects mice from colitis and colitis-associated cancer." (PMID 35399735, 2022). "Colitis mouse models exhibit reduced COMMD1 expression, indicating an inflammation-mediated response that may sustain chronic inflammation." (PMID 40370501, 2025).